ATRX (ATRX chromatin remodeler)
Diseases named in the same sentence as ATRX in open-access papers (continued):
Sharing a sentence is not in itself a finding about the gene and the disease.
neuroblastoma (continued). "To inactivate ATRX in the MYCN-amplified neuroblastoma cell lines, we designed and validated two guide RNAs (gRNA-2 and gRNA-5) to exon 6 of ATRX." (PMID 32060267, 2020). "Here we demonstrate that the DNA-replicative stress induced by ATRX mutations and MYCN amplification cause synthetic lethality in neuroblastoma." (PMID 32060267, 2020). "To analyze the epigenomic landscape in ATRX-mutant neuroblastoma cells, compared with that in wild-type ATRX neuroblastoma, we selected eight cell lines that encompass the major genetic groups, including those with MYCN amplification or ATRX mutations." (PMID 32060267, 2020). "In neuroblastoma, amplification of the MYCN oncogene and inactivation of the ATRX tumor-suppressor gene correlate with high-risk disease and poor prognosis." (PMID 32060267, 2020). "Ectopic MYCN caused metabolic reprogramming, mitochondrial dysfunction, ROS production, and DNA damage in ATRX-mutant neuroblastoma cells." (PMID 32060267, 2020). "In both ATRX-inactivated and ATRX-wild-type neuroblastomas bearing ALT activation, elongated telomeres were detected, which was associated with poor outcome in non-MYCN-amplified neuroblastoma." (PMID 31757062, 2019). "Driver genes/alterations, such as MYCN, 1p/11q deletion, ALK, ATRX and TERT, are characterized in high-risk neuroblastoma by previous studies, however, it is difficult to further stratify the high-risk neuroblastoma at molecular level." (PMID 30405689, 2018). "Genomic analyses for pediatric neuroblastoma have identified recurrent somatic mutations in cancer-related genes such as ALK, PTPN11, ATRX, MYCN, and NRAS." (PMID 28521285, 2017). "More recently, genome-wide searches for genetic alterations using whole-exome/genome sequencing have revealed that neuroblastomas, similarly to other pediatric malignancies, have very few additional gene targets, including ATRX, TERT, and RAS pathway genes." (PMID 29296183, 2017). "Other five genes (LRRC17, PXDN, FZD1, ARHGEF10L, ATRX) resulted to be expressed in neuroblastoma and involved in cell migration and invasion." (PMID 27009842, 2016). "High-throughput sequencing-based studies have highlighted that recurrent mutations of single genes are infrequent in primary neuroblastoma with activating mutations in ALK and inactivating mutations in ATRX, and TERT rearrangements being the most frequent." (PMID 27009842, 2016). "We only identified 2 mutated genes (ATRX and NEB) in this neuroblastoma patient that have been reported in the previous studies." (PMID 24147068, 2013). "To further confirm the identity of [GenBank:BE457721], we assessed the outcome of ATRX depletion on Arsd/e expression by RNA interference in the Neuro-2a cultured neuroblastoma cell line." (PMID 18842153, 2008). "GSEA showed significant upregulation of the same inflammatory response pathways and the epithelial-to-mesenchymal transition pathway in keeping with the ATRX knockout cell lines, suggesting that these distinct alterations of ATRX in neuroblastoma can both mediate this phenotype." (PMID 39892705, 2025). "Despite the challenges in the generation of ATRX mutant neuroblastoma models, our experiments in genetically engineered neuroblastoma cell lines identify cell-intrinsic changes in gene expression due to ATRX mutations that result in an inflammatory phenotype and macrophage recruitment." (PMID 39892705, 2025). "Although activation of the TMM has been shown to be a key factor in the poor prognosis of neuroblastoma, MYCN amplification and ATRX mutations, the primary drivers of the TMM, are also associated with multiple modes of transcriptional activation that drive malignant transformation." (PMID 40115016, 2025). "Here, the authors report two novel nonsense mutations in the ATRX gene in two unrelated older than 18 months of age children with advanced MYCN non-amplified neuroblastoma." (PMID 40286729, 2025).
neuroblastoma (continued). "In conclusion, we demonstrate differences in chromatin response to RA in neuroblastoma according to type of ATRX alteration and propose that within the ATRX subgroup, there is likely to be significant heterogeneity in response to differentiation therapies depending on the precise type of alteration." (PMID 41380652, 2025). "Ongoing work in our laboratory and others to model the biological effects of specific ATRX alterations at later stages of neural crest differentiation will provide further insight, in addition to much needed pre-clinical models of neuroblastoma for future studies." (PMID 41380652, 2025). "We next assessed whether RA treatment induced expression of direct RA HOX-gene targets in two neuroblastoma cell lines with in-frame ATRX deletions: SK-N-MM and CHLA-90." (PMID 41380652, 2025). "Additionally, in a limited cohort of available ATRX-altered neuroblastoma patient samples, we confirm findings from in vivo models and patient datasets showing a significant increase in macrophage infiltration." (PMID 39892705, 2025). "Our findings identify key differences in the tumor immune microenvironment in patients with ATRX mutant neuroblastoma that may, at least in part, explain the distinct clinical phenotype observed in these patients." (PMID 39892705, 2025). "The authors found two older children (NB1 and NB2) with advanced MYCN non-amplified neuroblastoma carried each one of the two following novel nonsense ATRX variants (p.Gln1670* or p.Glu1984*)." (PMID 40286729, 2025). "It has previously been described those changes in the ATRX gene (Alpha Thalassemia/Mental Retardation, X-linked) are the most common recurring events in the indolent clinical subtype (∼30 %) of MYCN amplified neuroblastoma." (PMID 40286729, 2025). "However, our data does not support clinical development of tazemetostat either alone or in combination with RA for ATRX IFF neuroblastoma." (PMID 41380652, 2025). "In direct contrast, the epigenetic response to RA is impaired in ATRX LoF neuroblastoma." (PMID 41380652, 2025). "ATRX loss-of-function from p.Gln1670* or p.Glu1984* mutations turn MYCN non-amplified neuroblastoma more aggressive and similar to what is seen in MYCN amplified neuroblastoma." (PMID 40286729, 2025). "On the other hand, few studies have detected an association between high-risk (stage IV) non-amplified MYCN neuroblastoma patients and mutant ATRX." (PMID 40286729, 2025). "Nonsense mutations in ATRX are scattered across the gene and can result in the absence of ATRX protein production; however, the impact of these mutations on neuroblastoma remains insufficiently studied." (PMID 39479502, 2024). "Finally, ATRX mutations, which are strongly associated with ALT, are frequently detected in high-risk neuroblastoma, especially in adolescents and young adults." (PMID 38837897, 2024). "Notably, SKNMM and CHLA-90 carry ATRX mutations, which are tightly associated with ALT and detected in a significant fraction of high-risk neuroblastoma found in adolescents and young adult patients." (PMID 38837897, 2024). "Almost all neuroblastoma patients with ATRX distortion suffer from ALT." (PMID 39479502, 2024). "All were diagnosed at <5 years of age and 1 has a MYCN amplified tumor, so these cases are not likely to represent ATRX mutated indolent neuroblastoma, common in older patients." (PMID 38200233, 2024). "The two distinct molecular expression patterns within ATRX aberrant neuroblastomas that we identified imply that there might be a need for distinct treatment regimens." (PMID 37540673, 2023). "For neuroblastoma there are only a few patient-derived ATRX aberrant models." (PMID 37540673, 2023).
neuroblastoma (continued). "Taken together, this suggests two opposing expression profiles within ATRX aberrant neuroblastoma." (PMID 37540673, 2023). "The most common ATRX aberration in neuroblastoma is a MED of exon 2–10 and therefore we visualized all the overlapping significantly changed genes sets with the same Normalised Enrichment Score (NES) directionality (i.e.–or +) between GI-ME-NΔ2–10, NB139Δ2–10, PDΔATRX and iTHERΔ2–10 in bubble plots." (PMID 37540673, 2023). "The most frequently harbored alterations of specific genes in neuroblastoma include heritable mutations in the ALK and PHOX2B observed in familial neuroblastoma, chromatin remodeling genes like ATRX, ARID1A and ARID1B and other important genes like PTPN11, MYCN, and NRAS." (PMID 37274289, 2023). "Therefore, we created isogenic ATRX aberrant models using CRISPR-Cas9 in several neuroblastoma cell lines and one tumoroid and performed total RNA-sequencing on these and the patient-derived models." (PMID 37540673, 2023). "Genomic correlates of indolent neuroblastoma, such as somatic alterations in the ATRX gene or activation of the alternative lengthening of telomeres (ALT) mechanism, have been defined, but we have been unsuccessful at leveraging these discoveries into more precise therapies." (PMID 37012551, 2023). "Together, the high somatic mutation frequencies and associations with other variants suggested a prominent role for mutations of chromosome 1 genes in the clinical spectrum of neuroblastoma, in addition to those of more established gene candidates like ALK and ATRX." (PMID 35768791, 2022). "cWGTS mapped events in TERT and ATRX in 8 (28%) and 5 (17%) neuroblastoma patients, respectively." (PMID 35585047, 2022). "The EUH subset includes (i) MYC-driven neuroblastoma expressing high MYC and/or MYCN protein, (ii) Neuroblastoma with TERT overexpression due to genomic rearrangements, and (iii) Neuroblastoma of the ALT group due to ATRX loss." (PMID 33968044, 2021). "In previous research in glioma, pancreatic neuroendocrine tumors, and neuroblastoma have demonstrated that ATRX mutations are associated with absence of ATRX protein." (PMID 34729095, 2021). "Additionally, other important genetic markers for neuroblastoma are mutations in ALK, PTPN11, TERT, ATRX, and amplification of MYCN." (PMID 34885007, 2021). "ATRX-mutant neuroblastomas have several unique features, relative to other ATRX-mutant cancers." (PMID 32060267, 2020). "This region is deleted in the ATRXIFDs in most ATRX-mutant neuroblastomas." (PMID 32060267, 2020). "However, in neuroblastomas, MYCN amplification and ATRX mutations are mutually exclusive and incompatible." (PMID 32060267, 2020). "To determine whether ATRX mutations and MYCN amplification are incompatible in vivo, we conditionally inactivated ATRX in two genetically engineered neuroblastoma mouse models 8,17,18." (PMID 32060267, 2020). "However, that cohort was relatively small and a much larger study of ATRX-mutant neuroblastomas would be required to determine if there is any genotype–phenotype correlation for the type of ATRX mutation." (PMID 32060267, 2020). "Other potential factors such as TERT rearrangements, ATRX mutations, CCND1 amplification may also perform well in prognosis of neuroblastoma." (PMID 31338261, 2019). "Moreover, ATRX is mutated in astrocytic tumours, HGG and in neuroblastoma, whilst DAXX deficiency has been linked to a few cases of paediatric HGG, with a mutually exclusive pattern to ATRX mutations." (PMID 28284043, 2017).
neuroblastoma (continued). "Thereby, the data raise the possibility that topoisomerase inhibitors (topotecan or irinotecan) might be clinically useful in neuroblastoma MYCN amplified or MYCN non-amplified patients with ATRX loss-of-function, as was observed in patient NB1." (PMID 40286729, 2025). "Therefore, we hypothesized that the combination of RA with EZH2 inhibition may have an additive effective for ATRX IFF neuroblastoma." (PMID 41380652, 2025). "Furthermore, the effect of ATRX nonsense mutations in MYCN non-amplified neuroblastoma has not been extensively studied in patients." (PMID 40286729, 2025). "Neuroblastoma cells with ATRX LoF also show decreased chromatin accessibility at neuronal differentiation genes following treatment with 13-cis-retinoic acid (RA) - an agent used as standard-of-care in the minimal residual disease setting to prevent neuroblastoma relapse." (PMID 41380652, 2025). "Therefore, the authors postulated that the complete loss of ATRX function in NB2 may have accelerated tumor growth and reduced median survival, uncovering the impact of ATRX loss of function in neuroblastoma proliferation, as observed in previous studies." (PMID 40286729, 2025). "The poor prognostic risk factors of locoregional neuroblastoma (LR-NB) include age, MYCN or MDM2-CDK4 amplification, 11q, histology, diploidy with ALK or TERT mutations, and ATRX aberrations." (PMID 38730688, 2024). "However, in ATRX-wild type ALT-positive neuroblastomas, ATRX protein levels were found to be significantly decreased, suggesting that impaired ATRX activity could still underlie ALT in these cases." (PMID 39635126, 2024). "By studying the association of mutational variants of candidate neuroblastoma genes with clinical, cytogenetic and pathological characteristics, and survival outcomes, we found 1p candidate genes CHD5 and KIF1Bβ to be most frequently mutated after ALK, ATRX, and BARD1." (PMID 35768791, 2022). "Therefore, metabolic pathways related to dopamine in the ATRX-cluster might be distinct from other neuroblastoma cases." (PMID 33465163, 2021). "Thus, the combination of VMAT inhibitor with COMT/MAO inhibitor (MYCN-cluster) or MIBG radiation therapy (ATRX-cluster) might be a potential therapeutic strategy for treating neuroblastoma cases." (PMID 33465163, 2021). "This may be why ATRX-mutant neuroblastomas are slow growing and indolent." (PMID 32060267, 2020). "However, no increase in neuroblastoma incidence has been observed in children with XLMR suggesting that ATRX mutations alone are not sufficient to induce neoplasia." (PMID 30760980, 2019). "Several recurrently mutated genes or loci which correlated with high-risk neuroblastoma have been identified, such as ALK mutations or amplifications, PHOX2B mutation, chromosome 1p and 11q deletions, truncating or structural variants of ATRX gene, genomic rearrangements of TERT." (PMID 30405689, 2018). "However, how ATRX LoF affects neuroblastoma differentiation potential is unknown." (PMID 41380652, 2025). "Furthermore, inhibiting EZH2 in neuroblastoma (NB) patients upregulates genes related to neuronal maturation, inducing apoptosis in ATRX in-frame fusion (IFF) NB cells." (PMID 39479502, 2024). "In this study, we characterized a Swedish neuroblastoma cohort with the focus on telomere maintenance mechanisms (TMMs), i.e., MYCN amplification and the juxtapositioning of TERT and ATRX aberrations." (PMID 38136279, 2023). "In line, we detected 29 MYCN-amplified neuroblastomas, but also 42 TERT rearrangements and 8 ATRX alterations." (PMID 34442335, 2021). "Also in the absence of an ATRX alteration the underlying drivers of ALT neuroblastoma are currently unknown, and somatic alterations in other genes, known to be associated with ALT in other malignancies are rarely found in neuroblastoma." (PMID 32375866, 2020).
neuroblastoma (continued). "We showed earlier that tumors with ATRX deletions tend to have higher adaptive immune expression, and we found a similar pattern in an independent set of MYCN-NA neuroblastoma samples." (PMID 32275708, 2020). "Even when whole-genome sequencing of neuroblastoma was conducted, few recurrent gene alterations (MYCN, ALK, ATRX and TERT) were identified." (PMID 29311760, 2018). "CODEX's normalization and segmentation accuracy is further evaluated through the analysis of the WES data of 222 neuroblastoma matched tumor/blood samples from the TARGET project, with a focus on the well-studied ATRX gene region." (PMID 25618849, 2015). "We further evaluate performance on 222 neuroblastoma samples with matched normals and focus on a well-studied rare somatic CNV within the ATRX gene." (PMID 25618849, 2015). "All described aberrations presented below – from chromothripsis to gene deletions, like ATRX, ARID1A and ARID1B genes – have, so far, only been described by sequencing methods of the neuroblastoma genome." (PMID 25161957, 2014). "Therefore, ATRX mutations and the downstream deregulated ALT may provide a key to understand the tumor biology and an opportunity for novel therapies in the late onset neuroblastoma patients." (PMID 24147068, 2013). "In ATRX IFF neuroblastoma it has been shown that differentiation block is mediated by a non-canonical function of the ATRX IFF, activating REST and resulting in repression of neurogenesis genes." (PMID 41380652, 2025). "ATRX gene variants may play an important role in identifying more effectively those patients who will have an increased risk of developing chronic or indolent MYCN non-amplified neuroblastoma, and should be considered for future target therapies and therapeutic approaches." (PMID 40286729, 2025). "Our data indicates that cells of a myeloid rather than lymphoid lineage are particularly enriched in ATRX mutant neuroblastomas." (PMID 39892705, 2025). "According to genome aberrations, high-risk neuroblastomas can be divided into four categories: MYCN amplification (37%), TERT rearrangement (23%), lack of ATRX (11%), and not mutant (29%)." (PMID 39479502, 2024). "Moreover, ATRX is involved in the development of cancers involving ALT, such as neuroblastoma, pancreatic neuroendocrine tumors and osteosarcoma." (PMID 39479502, 2024). "While neuroblastoma cells harboring ATRX mutations are thought to rely on ALT to maintain telomere lengths, a recent study has shown that neuroblastoma tumors can also be negative for both ALT and telomerase." (PMID 38837897, 2024). "There are additional UH neuroblastomas, which do not exhibit MYC-family protein overexpression, TERT overexpression and ATRX (or DAXX) loss." (PMID 35053227, 2022). "Thus, neuroblastoma cases in the ADRN-cluster were classified into two genetically distinct clusters, MYCN- and ATRX-clusters." (PMID 33465163, 2021). "CUX2 is a direct MYCN target and is upregulated in MYCN-amplified neuroblastomas but not ATRX-mutant neuroblastomas." (PMID 32060267, 2020). "Knocking down ATRX decreased colony formation in MYCN-amplified neuroblastoma cells (IMR32 and NB-5) but not cell lines expressing wild-type MYCN." (PMID 32060267, 2020). "The CUX2 promoter is epigenetically repressed by H3K27me3 in ATRX-mutant neuroblastomas and not induced in SKNMM cells in the presence of doxycycline." (PMID 32060267, 2020). "However, in human neuroblastoma TERT rearrangements rarely, if ever, co-occur with MYCN or ATRX alterations." (PMID 29492199, 2018). "All two ATRX mutations showed reduced or absence of ATRX protein production in MYCN non-amplified neuroblastoma, as observed by immunohistochemistry and it may have affected the normal ATRX protein expression." (PMID 40286729, 2025). "•Inactivation of the ATRX tumor suppressor in MYCN non-amplified neuroblastoma." (PMID 40286729, 2025).